CRP (C-reactive protein)
Diseases named in the same sentence as CRP in open-access papers (continued):
Sharing a sentence is not in itself a finding about the gene and the disease.
prostate carcinoma (continued). "We seek to establish whether CRP levels reflect inflammation caused by non-metastatic prostate cancer before and in response to RT with or without prior androgen ablation (AA)." (PMID 34926085, 2021). "Similarly, the weighted-median method also showed that circulating levels of CRP were not causally associated with prostate cancer risk (OR 1.00, 95% CI 0.93 to 1.08, and P = 0.96)." (PMID 33178578, 2020). "Logistic regression analysis revealed that age, PSA, PSAD, serum WBC count, neutrophil fraction, monocyte fraction, and MLR were significantly associated with high Gleason score prostate cancer, whereas other fractions of WBCs (lymphocytes, basophils, and eosinophils), CRP level, and NLR were not." (PMID 27823973, 2017). "Logistic regression analysis yielded that men with the highest CRP values had greater odds of having higher household incomes and lower odds of having received higher education, being aged 40 years or older, being of a race or ethnicity different from other, and of having prostate cancer." (PMID 26380255, 2015). "Glycosylation of human CRP and its carbohydrate binding properties under different pathological conditions may serve as a marker of disease and influence its biological function in prostate cancer." (PMID 26380255, 2015). "In addition, authors suggest that plasma CRP measurements may help to differentiate benign conditions from prostate cancer in patients with elevated serum PSA levels." (PMID 22963460, 2012). "Patients should get a standard set of labs and PSA to check for recurrence of prostate cancer as well as inflammatory markers such as the erythrocyte sedimentation rate (ESR) and C-reactive protein (CRP) along with the white blood cell (WBC) count." (PMID 37686515, 2023). "High CRP levels were reported to be an OS and PCS predictor in prostate-cancer patients, which is consistent with the present study in a meta-analysis." (PMID 36289628, 2022). "Pre-therapeutic LDH, HB, CRP, ALP and GGT level are helpful parameters for prediction of overall survival of patients receiving Lu-177-PSMA-617-RLT for metastasized prostate cancer." (PMID 35788220, 2022). "Moreover, because conventional observational studies are susceptible to potential bias such as unmeasured confounders and reverse causality, it remains unclear whether the association of CRP with prostate cancer risk is causal or not." (PMID 33178578, 2020). "Lastly, we measured the serum levels of the inflammation marker C-reactive protein (CRP) in 119 BPH patients and 175 prostate cancer patients." (PMID 28160568, 2017). "Pro-inflammatory markers such as IL-6, IL-8, CRP and TNF-α have shown to be elevated beyond normal levels in both breast and prostate cancer patients experiencing CRF." (PMID 28895922, 2017). "It is interesting in our study, therefore, that prostate cancer patients showed the most benefit (in terms of reduced PSA and CRP levels) from IVC therapy." (PMID 22963460, 2012). "The aim of the present study was to examine the relationship between interleukin-6 and C-reactive protein in patients with benign disease (BPH) and in prostate cancer." (PMID 15505624, 2004). "Findings were also null for CRP, IL-1β, and TNF-α in these two prostate cancer cohorts." (PMID 37213604, 2023). "The result showed that combined progressive aerobic exercise (AE) and resistance training (RT) in prostate cancer patients undergoing androgen suppression therapy showed significant improvement in QOL, decreased tiredness, and lower C-reactive protein (CRP) levels." (PMID 35935260, 2022). "CRP levels do not correspond with the immune effects of locally advanced prostate cancer or its treatment." (PMID 34926085, 2021). "This expected PSA decline without appreciable change of CRP, lymphocytes, and WBCs appears to indicate that none of these factors accurately measure inflammatory changes from early prostate cancer suppression or eradication." (PMID 34926085, 2021).
prostate carcinoma (continued). "Prostate cancer has been a focal point of many publications investigating serum CRP as a potentially important biomarker for nonmetastatic prostate cancer." (PMID 34926085, 2021). "Our results demonstrate a lack of clinical utility for CRP as a marker of the inflammatory effects of non-metastatic prostate cancer." (PMID 34926085, 2021). "CRP is not a sensitive marker of the acute inflammatory effects of non-metastatic prostate cancer and treatment response with androgen ablation or radiation therapy." (PMID 34926085, 2021). "In agreement with previous prospective studies, circulating CRP concentrations were not related to prostate cancer incidence or mortality in the current study." (PMID 32963348, 2020). "As one would expect, a significant RT-induced increase of the CRP level was noted in HNSCC patients but not in prostate cancer patients." (PMID 28248265, 2015). "We found that high CRP values indicating high inflammation were not positively correlated with the occurrence of prostate cancer." (PMID 26380255, 2015). "The significance of C-reactive protein (CRP), an inflammatory and innate immunity molecule, has not been evaluated thoroughly in prostate cancer (PC)." (PMID 19436291, 2009). "First, patients were selected on the basis of availability of PSA, C-reactive protein and albumin, therefore this cohort of patients might not be representative of all the prostate cancer patients diagnosed and treated in the area." (PMID 23768149, 2013).
hypercoagulability (91 papers, 2006 to 2026). "The laboratory results demonstrate that hypercoagulability is associated with excessive production of inflammatory markers, including Interleukin‐6 and Interleukin‐8, fibrinogen, and CRP, along with increased levels of inflammatory cells in neutrophilia and monocytosis." (PMID 40366340, 2025). "For further evaluating whether XFC can alleviate inflammation and hypercoagulability in AA rats, RA diagnostic indicators (RF and CRP), inflammatory factors (IL-6and IL-10), and coagulation indicators (FBG and DD) were detected." (PMID 39376558, 2024). "Some patients still displayed markers of hypercoagulability (i.e., high D-dimer) and an increased inflammatory response (i.e., high CRP), which may increase the risk of thromboembolic events and death after hospitalization and during recovery." (PMID 37092518, 2023). "In addition, the logistic multivariate analysis model demonstrated that D-dimer, CRP levels, and lymphocyte counts were the main risk factors for disease severity, which has a relationship with inflammation and hypercoagulation." (PMID 32892540, 2021). "In addition, HSA was associated with markers of systemic inflammation and hypercoagulation (interleukin 6, tumour necrosis factor α, C-reactive protein, fibrinogen and D-dimer)." (PMID 34948066, 2021). "Thereby, CRP may play a crucial role in hypercoagulability caused by MP infection." (PMID 33545964, 2021). "This gram-negative bacilli infection increases fibrinogen, blood leukocytes, and homocysteine levels, stimulates the release of C-reactive protein (CRP), induces hypercoagulability, and increases the production of proinflammatory inflammatory metabolites." (PMID 40102932, 2025). "This can explain the episodes of intense hypercoagulability in severely ill patients with higher levels of CRP, WBC, and LHD." (PMID 40142778, 2025). "In other words, a higher CRP at 21 days post-burn predicted a tendency toward hypercoagulability, reflected in a shorter APTT." (PMID 38792336, 2024). "Other suggested VTE biomarkers include markers for thrombophilia, for instance, soluble P-selectin and C-reactive protein (CRP)." (PMID 37569483, 2023). "While these studies did not link the results to risk of VTE recurrence, a sub-study of the Leiden Thrombophilia Study followed those with a prior DVT and assessed circulating CRP levels at least 3 months after discontinuation of oral anticoagulation." (PMID 36177015, 2022). "Causes of AIS are often multifactorial but may be linked to inflammatory and hypercoagulability states in MIS-C; this can be detected through high D-dimer and low fibrinogen levels, along with ESR and CRP inflammatory markers." (PMID 41226731, 2025). "For instance, C-reactive protein can simultaneously affect the balance of the complement and fibrinolysis systems and promote platelet adhesion and the expression of tissue factor, all of which can lead to a hypercoagulable state." (PMID 39742024, 2024). "The additional use of laboratory tests for inflammation, hypercoagulability, and organ damage (eg, C-reactive protein, D-dimer, and cardiac enzymes) may assist in early identification and subsequent management." (PMID 37970101, 2023). "Prolonged clotting tests combined with high levels of CRP and antiphospholipid antibodies, which are active in vitro anticoagulants, may mask the true hypercoagulability." (PMID 34381066, 2021). "Inflammatory markers (CRP, IL-6) and d-dimer were elevated, indicating a hypercoagulable state." (PMID 32501751, 2020). "In patients with occult cancer, compared to patients with active known cancer, the impact of paraneoplastic hypercoagulability may be smaller as markers of coagulation (D-dimer) and inflammation (CRP and Hb) tend to be less altered at admission in the first group." (PMID 37021282, 2023).
hypercoagulability (continued). "Thus, the lower level of CRP (but elevated procalcitonin) in this patient group could be explained by decreased synthetic liver function and elevated D-dimer with hypercoagulation (or hyper coagulopathy)." (PMID 34576853, 2021). "The Leiden Thrombophilia study found patients with a prior VTE had higher CRP levels than healthy controls, when circulating CRP was measured between 6 and 18 months following acute VTE." (PMID 36177015, 2022). "Severely ill patients with intense hypercoagulability had higher D-dimer levels, indicating increased thrombosis rates, as well as elevated levels of lactate dehydrogenase activity in plasma (LDH), C-reactive protein (CRP), and white blood cell counts (WBC)." (PMID 40142778, 2025). "In contrast, the correlation with declining oxygen requirement, trend with increasing hypercoagulability (increasing d-dimer) in the absence of systemic inflammation (CRP), is likely attributable to respiratory microvascular thrombosis." (PMID 34401683, 2021). "Total hemoglobin increased 1.2–1.9 g/dL even as reticulocyte counts decreased, reflecting the better efficiency and quality of HbF-enriched erythropoiesis, also shown by improvements in biomarkers of hemolysis, thrombophilia, and inflammation (LDH, bilirubin, D-dimer, CRP)." (PMID 28880867, 2017). "Also indicating better RBC quality, biomarkers of hemolysis, thrombophilia, and inflammation (LDH, bilirubin, D-dimer, C-reactive protein [CRP]) improved." (PMID 28880867, 2017). "Centenarians, mainly females, present markers of inflammation [e.g. increased plasma levels of IL-6 and CRP (C-reactive protein) and hypercoagulable state], but do not suffer most of the detrimental effects of inflammaging." (PMID 27555614, 2016). "The hypercoagulable state in the abnormal TEG group may be attributed to the severe inflammatory response in these patients, as reflected by higher levels of CRP, LDH, and D-dimer, which are known to activate the coagulation cascade and promote hypercoagulability." (PMID 39911585, 2025). "Levels of IL-6, sCD14 and sCD163 (both released by monocytes/macrophages), non-specific markers of inflammation (such as C-reactive protein and cystatin C), and markers of hypercoagulation and microbial translocation are variably increased during HIV-1 infection." (PMID 36672667, 2023).
non-small cell lung carcinoma (89 papers, 1996 to 2026). A group of at least three distinct histological types of lung cancer, including non-small cell squamous cell carcinoma, adenocarcinoma, and large cell carcinoma. "Studies have shown that specific airway microbiota compositions are linked to systemic inflammation in conditions like non-small cell lung cancer, where CRP levels are used as an indicator of inflammation." (PMID 41395466, 2025). "A total of 387 NCSLC patients of all stages were included in the “post-diagnostic C-reactive protein and albumin predict survival in Chinese patients with non-small-cell lung cancer: a prospective cohort study”." (PMID 38540301, 2024). "C-reactive protein (CRP) concentrations have been associated with advanced non-small-cell lung cancer and poor prognosis." (PMID 38001689, 2023). "Recently, a study revealed that high serum CRP level was significantly associated with PD-L1 (programmed death-ligand 1) positivity in patients with non-small cell lung cancer." (PMID 31260491, 2019). "More interestingly, a study found that high level of preoperative serum CRP was significantly associated with PD-L1 positivity in 508 patients with non-small cell lung cancer." (PMID 31260491, 2019). "Preoperative serum CRP levels are reported to be associated with tumor size in non-small cell lung cancer." (PMID 29513714, 2018). "The extent of weight loss, albumin, C-reactive protein, performance status and quality of life was measured in 106 patients with inoperable non-small cell lung cancer (stages III and IV)." (PMID 12177792, 2002). "In addition, systemic inflammatory response markers such as C-reactive protein (CRP) have been associated with poor prognosis in patients with many types of cancer, including non-small cell lung cancer, one of the leading causes of cancer-related deaths worldwide." (PMID 33534859, 2021). "Our findings show that among the investigated inflammatory indices, C-reactive protein/albumin ratio has the highest prognostic value in patients with metastatic non-small cell lung cancer." (PMID 40465984, 2025). "Several other studies have demonstrated a correlation between early CRP kinetics and improved response in metastatic urothelial carcinoma (mUC) and non-small cell lung cancer (NSCLC)." (PMID 41306979, 2025). "In non-small cell lung cancer, a relationship between inflammatory markers CRP and CD66b+ TANs has been demonstrated, and the same result was found in our present work." (PMID 41438682, 2025). "A study focusing on non-small cell lung cancer patients found that dynamic changes in CRP levels, specifically an initial increase followed by a decrease, were predictive of a positive response to immunotherapy and improved OS." (PMID 38304429, 2024). "Two studies recently demonstrated the prognostic power of early CRP kinetics, such as flare response, in metastatic renal cell carcinoma (mRCC) and advanced non-small cell lung cancer (NSCLC) as early as 4 weeks after ICI initiation." (PMID 37603206, 2023). "Non-small cell lung cancer patients with CRP levels higher than 40 mg/L were more likely to suffer from metastatic systemic cancer with a specificity of 100%." (PMID 37382699, 2023). "In such studies, survivors of childhood ALL exhibiting poor sleep were found to have elevated plasma levels of IL-6, IL1b and CRP, and elevated IL-6 levels were correlated to poor sleep in non-small cell lung cancer patients receiving chemoradiotherapy." (PMID 36213755, 2022). "In this study, we explored the utility of changes in serum C-reactive protein (CRP) levels as a potential on-treatment surrogate of OS in two randomized clinical trials of atezolizumab (anti-PD-L1) monotherapy in second-line non-small cell lung cancer (NSCLC)." (PMID 33534859, 2021). "We evaluated serum C-reactive protein (CRP) in non-small cell lung cancer (NSCLC) trials with atezolizumab (anti-PD-L1) as an early OS surrogate." (PMID 33534859, 2021).
non-small cell lung carcinoma (continued). "The GPS was first presented as a scoring system based on a combination of CRP and albumin in patients with inoperable non-small cell lung cancer." (PMID 33227100, 2020). "More interestingly, a study revealed that the high level of serum CRP was significantly correlated with PD-L1 (programmed death-ligand 1) positivity in patients with non-small-cell lung cancer." (PMID 31998420, 2020). "In patients received non-small cell lung cancer resection, the research proposed by Shinohara showed that elevated 6-week postoperative C-reactive protein were related to worse OS." (PMID 31533862, 2019). "Although the reasons for elevated CRP levels in cancer patients is not clearly understood, other studies have also supported CRP as an indicator of poor outcome in non-small cell lung cancer." (PMID 28402963, 2017). "Recently, CRP was also found to be a monitor of chemotherapy response in advanced non-small cell lung cancer." (PMID 24130817, 2013). "The GPS was originally developed, from the combination of C-reactive protein and albumin, in a cohort of patients with advanced non-small cell lung cancer." (PMID 21266974, 2011). "This work is consistent with previous work in patients with inoperable non-small-cell lung cancer and improves on the prediction of survival using an elevated C-reactive protein alone." (PMID 16404432, 2006). "Interleukin-6 is an important independent mediator of elevated C-reactive protein concentrations in patients with non-small-cell lung cancer." (PMID 15570310, 2004). "CRP was reported as a diagnostic marker for ICC, and serum CRP flare could predict the response to anti-PD1 treatment in non-small cell lung cancer." (PMID 41409288, 2025). "It is of interest that recent machine learning models of prognostic factors, in patients with non-small cell lung cancer receiving immunotherapy in the context of a randomized trial, have identified albumin, CRP, LDH and neutrophils as independent prognostic factors." (PMID 40133911, 2025). "The key to the role that these markers can play in predicting the prognosis of non-small cell lung cancer may be due to the role of Alb, CRP, and peripheral blood cells in the immune microenvironment of non-small cell lung cancer." (PMID 37036321, 2023). "These hypotheses are supported by recent studies highlighting CRP as the most prognostic clinicopathological marker for survival in non-small cell lung cancer (n=751) and urothelial cancer (n=896) cohorts treated with the ICI atezolizumab." (PMID 35978814, 2022). "Similarly, in Non-Small Cell Lung Cancer patients with CRP levels higher than 40 mg/L were more likely to have a metastatic disease with a specificity of 100%." (PMID 33562331, 2021). "In fact, the serum CRP level before treatment has been proven to be an independent prognostic factor in hepatocellular, esophageal, renal, bladder, prostate, colorectal, ovarian, pancreatic, and non-small cell lung cancer." (PMID 29668751, 2018). "The acute inflammatory, as manifest by alterations in white cell count and circulating concentrations of acute-phase proteins, C-reactive protein (CRP), and albumin, has been shown to be an independent prognostic factor in various cancers including non-small cell lung cancer (NSCLC)." (PMID 21569644, 2011). "We therefore measured body mass, body composition, energy expenditure, energy intake and C-reactive protein (CRP) over several cycles of chemotherapy among patients considered to be at high (non-small-cell lung cancer (NSCLC)) and metastatic melanoma, and low (metastatic breast) risk of wasting." (PMID 15726121, 2005). "Studies also showed that CRP was an independent determinant of survival in non-small-cell lung cancer and could be useful in the initial evaluation of patients with small cell lung cancer and in monitoring response to therapy." (PMID 16117833, 2005).